CCR7 (C-C motif chemokine receptor 7)
Diseases named in the same sentence as CCR7 in open-access papers (continued):
Sharing a sentence is not in itself a finding about the gene and the disease.
tumor (continued). "Preclinical data showed the emergence of a highly immunosuppressive subpopulation expressing lipid droplets and CC chemokine receptor 7 (CCR7), migrating from tumour tissues to lymphoid organs, such as the thymus and spleen." (PMID 40574837, 2025). "CD4+ central memory T cells (Panel2-C17) also exhibited elevated CCR2 and CCR7 expression, potentially facilitating tumor-directed migration." (PMID 41194936, 2025). "For instance, the HybridDC nanovaccine, incorporating CCR7, tumor antigens, and costimulatory molecules, enhances precise targeting to lymphoid tissues, improving antigen delivery and reshaping the tumor immune landscape." (PMID 40083941, 2025). "It is suggested that blocking the CCR7 signal on HCC tumor cells enhances their sensitivity to sorafenib." (PMID 40685403, 2025). "Here, the authors show that sequential tumor-directed radiotherapy and PD-1 inhibition and migratory CCR7+ dendritic cells are required for complete and durable tumor responses in HNSCC." (PMID 40675962, 2025). "In this study, we found that CCR7 was expressed in both tumor cells and stromal cells through the IHC analysis of TMA, spatial transcriptome and single-cell sequencing analysis of HCC tissues, but their effects were opposite." (PMID 40685403, 2025). "Following the uptake of tumour‐derived material, activated cDCs acquire the expression of the chemokine receptor CCR7, facilitating their migration to tumour‐draining LNs (tdLNs)." (PMID 40878038, 2025). "Across carcinomas, tumor-retained CCR7+ migratory dendritic cells downregulate antigen-presentation programs with dwell time, implying that retention within the tumor parenchyma diminishes cross-priming potential." (PMID 41487561, 2025). "DCs located in DC_3 with the high expression of Ccr7 and Fscn1 displayed a mregDC (mature DC enriched in regulatory molecules) signature, which was crucial for inducing tumor‐directed T‐cell responses." (PMID 39574346, 2025). "Ironically, immature DCs in tumor tissues have been found to enter an intrinsic activation process, followed by upregulation of chemokine receptor 7 (CCR7), for improved motility towards lymph nodes, where they can present tumor antigens efficiently." (PMID 40940953, 2025). "The representative images of H&E staining (Left) and CCR7 expression of the spatial cluster distribution (Right) from one patient's tumor tissue were presented." (PMID 40685403, 2025). "After acquiring tumor antigens, mature DCs migrate to lymph nodes by expressing the CCR7 chemokine receptor, which enables efficient antigen presentation to T cells via MHC complexes." (PMID 40977690, 2025). "CD4+ central memory T cells exhibited activation phenotypes, including upregulation of CD127 and CCR7, supporting anti-tumor responses by sustaining immune memory and survival signals." (PMID 41194936, 2025). "Specifically, we demonstrate that activated, migratory CCR7+ dendritic cells are requisite for the complete tumor response to immunoradiotherapy." (PMID 40675962, 2025). "The chemokine receptors CCR6, CCR7, CXCR3, CXCR4, CXCR5, and CXCR6 have the highest expression across lymphocytes, and CCR8, a known hallmark of tumour infiltrating Treg cells, is exclusively expressed on Treg cells." (PMID 39915477, 2025). "CCR7 is typically expressed in SS, and its levels are also elevated in advanced-stage MF, particularly in cases with tumor lesions and lymph node involvement." (PMID 40861461, 2025). "Cholesterol efflux in response to LXR ligands derived from tumour cells has been shown to promote cancer immune escape by inhibiting DC migration to the tdLN through downregulation of CCR7." (PMID 40878038, 2025). "In this study, we systematically administered VEGF-C to orthotopic HCC mouse models, which promoted intratumoral lymphangiogenesis to provide pathways for CCR7+ monocytes, CCR7+ MΦs, and CCR7+ T cells to enter the tumor." (PMID 40685403, 2025).
tumor (continued). "This maturation process triggers the upregulation of CCR7 expression, vital for the migration of cDC1s from tumor sites to TDLNs." (PMID 39420203, 2024). "So, we used CCL21 or CCR7 antibodies to block the migration of pDCs in response to CCL21 protein or tumor co-culture conditions." (PMID 39456552, 2024). "We found that CCR7+ DCs were heterogeneous, influenced by duration of tumour residence, location (tumour versus dLN), and anti-PDL1 treatment." (PMID 38267413, 2024). "In PICseq data from NSCLC38, we found that doublets containing CCR7_DCs highly expressed ligands we identified in murine tumours, and their corresponding T cell receptors were highly expressed in the same CCR7_DC-T cell conjugates." (PMID 38267413, 2024). "The CCR7-targeting CAR-M presented antigen-specific cytotoxicity to combat tumor cells, reducing the tumor metastasis and prolonging overall survival in breast cancer." (PMID 39175095, 2024). "T cells isolated from central, peripheral, and non-tumor tissues predominantly displayed an effector memory phenotype (CD45RA− CCR7−)." (PMID 38335302, 2024). "Of note, the activated, tumour-experienced BMDCs generated by this system also expressed OX40L and PVR, resembling the phenotype of tumour-retained CCR7+ DC in vivo." (PMID 38267413, 2024). "Altogether, data from these treatment cohorts support the importance of an ICB-activated tumour-residing CCR7+ DC state." (PMID 38267413, 2024). "Specifically, CD80 and CD86 were higher in tumour-residing CCR7+ DCs, confirmed at a protein level, while Icosl was significantly higher in migrated CCR7+ DCs in the dLN." (PMID 38267413, 2024). "CCR7+ DCs cluster around tumour blood vessels and both recruit cytotoxic T cells via production of CXCL16 and ensure their survival due to trans-presentation of IL-15." (PMID 38223410, 2024). "To investigate the effects of anti-PD-L1 on CCR7+ DC-CD8+ T cell interactions in tumours, we first analysed scRNA-seq of TILs, focussing on PD-1 (Pdcd1)-expressing CD8+ T cells which are the target of PD-L1–PD-1 checkpoint blockade." (PMID 38267413, 2024). "Can the combination and indicators such as VEGF-C, CCR7 and tumor markers improve the accuracy of diagnosis?" (PMID 37307828, 2024). "The knockdown of CCR7 decreased tumor cell proliferation, migration, and invasion in vitro using the TNBC cell lines, 4T1 and MDA-MB-231, and reduced the distant metastasis of 4T1 cells in an orthotopic mouse model." (PMID 39001456, 2024). "Pan-cancer analysis revealed that CCR7 was highly expressed in various tumours and that the high CCR7 expression group had better overall and disease-free survival in patients with pan-cancer." (PMID 38762550, 2024). "Subsequently, we investigated the correlation between CCR1, CCR5, and CCR7 and the degree of immune cell infiltration in the tumor microenvironment." (PMID 38552222, 2024). "Of note, CCR7+DCs derived from cDC1s almost retain in tumor site and enhance anti-tumor immunity through mediating the expression of various chemokines and cytokines which are essential in the function of T cells and NK cells." (PMID 39493763, 2024). "Activated DCs (defined in this study as surface CCR7+PD-L2+, hereafter just “CCR7+ DC”) were a prominent tumour DC population, and this was confirmed by flow cytometry." (PMID 38267413, 2024). "These tumour-retained CCR7+ DCs are phenotypically and transcriptionally distinct from their dLN counterparts and heterogeneous." (PMID 38267413, 2024). "Even more, we identified a cDC2 population expressing the Fc gamma receptor I (FcγRI)/CD64 in tumors and LN that displayed high levels of CD40 and CCR7 indicating involvement in T cell-mediated tumor immunity." (PMID 38631706, 2024). "CCL19 or CCL21 binding to CCR7 activates signaling pathways in tumor cells, including PI3/Akt, MAPK/ERK, and Jak/STAT, thereby enhancing VEGF-C expression." (PMID 37307828, 2024).
tumor (continued). "Both scRNA-seq and RNA-seq dataset analyses suggested that tumour tissues had significantly higher CCR7 expression than normal bladder tissues." (PMID 38762550, 2024). "In this tumor-free scenario, we observed that CCR7 and CD62L seemed to promote stronger LN homing compared to the other conditions explored involving only one or two of the selected molecules in this study." (PMID 38769377, 2024). "Then, we found that intrapleural injection of LLC-EVs did not increase the frequency of DCs in lung tumors or suppress tumor growth in Ccr7-/- mice." (PMID 38250037, 2024). "We found that CCR7 increased on DCs from tumor injection site draining lymph node after the α-LNP administrated in vivo, demonstrating that α-LNP increased the recruitment of APCs to lymphoid tissue and further drove the adaptive immune response." (PMID 39065637, 2024). "When silencing VEGF-C, it had an inhibitory effect on the expression of VEGFR-2, VEGFR-3, CXCR4, and CCR7, and regulated tumor cells proliferation and invasion through AKT, ERK, and p38 signaling pathways." (PMID 38566083, 2024). "Altogether, these data support the conclusion that tumour CCR7+ DC states can be manipulated to promote antigen-specific CD8+ T cell responses." (PMID 38267413, 2024). "Compared to Kaede-red tumour emigrants in the dLN, CCR7+ DCs in tumours were enriched in ‘interferon gamma response’ genes." (PMID 38267413, 2024). "Our data help to resolve these contradictions; We propose that tumour CCR7+ DCs are heterogeneous, with subset-specific capacities to both support and inhibit the cytotoxic T cell niche, presenting new opportunities for intervention." (PMID 38267413, 2024). "Since tumour-retained CCR7+ DCs are reduced in their migratory capacity, we sought to assess how their transcriptional programmes changed with increasing time in the tumour." (PMID 38267413, 2024). "To identify transcription factors (TF) that accompany the tumour-retained CCR7+ DC state, we performed TF regulon analysis, which revealed that Tcf7 expression and activity were upregulated in terminal CCR7+ DC states." (PMID 38267413, 2024). "In this study, we combined scRNA-seq with a photoconvertible murine tumour model to unravel the spatio-temporal dynamics of tumour CCR7+ DCs." (PMID 38267413, 2024). "On the other hand, certain CCR7-expressing tumor cells can also use this to undergo lymphatic metastasis, leading to tumor spread and metastasis." (PMID 37307828, 2024). "Strikingly, tumour-retained CCR7+ DCs were phenotypically distinct from those that migrated to the dLN and took on an increasingly “exhausted” transcriptional profile with more prolonged tumour dwell-time." (PMID 38267413, 2024). "We found that CD80 and CCR7 increased on DCs from tumor-infiltrating lymph nodes, suggesting that the α-LNP improves the LNDC maturation and boosts its migration ability." (PMID 39065637, 2024). "Tumour dendritic cells (DCs) internalise antigen and upregulate CCR7, which directs their migration to tumour-draining lymph nodes (dLN)." (PMID 38267413, 2024). "Contrary to current assumptions, CCR7+ DCs are heterogeneous, including sub-populations that either primarily contribute to LN migration or are retained in the tumour." (PMID 38267413, 2024). "Only 9% of DCs in the dLN resembled Ccr7_DC.2/3, despite Ccr7_DC.2/3 being the dominant Kaede-red tumour CCR7+ DC states." (PMID 38267413, 2024). "DCs expressing activation transcripts have been identified in tumour-dLNs5,30 and CCR7 expression directs migration to the dLN." (PMID 38267413, 2024). "CCR7 usually promotes tumor migration in the TME, and notably, the LXR activation inhibits the CCR7 in DC cells by upregulating SOCS3 and thus inhibits cancer migration." (PMID 38550382, 2024). "The functional enrichment analysis of tumor cells indicated that CCR7 gene knockout not only affected the enrichment of key signaling pathways in tumor cells but also affected the metabolic pathways of tumor cells." (PMID 38539232, 2024).
tumor (continued). "Similar results were observed in the wound healing assay and CCK-8 assay, indicating that CCR7-induced M2 polarization can promote tumor cell survival, migration and invasion." (PMID 38539232, 2024). "scRNA-seq of Kaede-red CD45+ cells in tumour-dLNs (integrated with CD45+ cells from control LNs) included a prominent Ccr7+Cd274+Pdcd1lg2+ DC cluster among myeloid cells." (PMID 38267413, 2024). "The prevalence of tumour-retained Kaede-red CCR7+ DCs was validated over a time-course in all tumour models, by flow cytometry, where CCR7+ DCs were the major Kaede-red DC cell-type up to 72 h post-photoconversion." (PMID 38267413, 2024). "The immunohistochemical results for CCR7 indicate that CCR7 is expressed in tumor cells of the KO and WT groups, but in stroma cells, the expression level of CCR7 in the KO group was significantly lower than that in the WT group." (PMID 38539232, 2024). "Altogether, these data provide further insight to tumour CCR7+ DC dynamics and their role in cancer immunotherapy." (PMID 38267413, 2024). "To investigate the mechanisms by which CCR7+ DCs promote anti-tumour immunity, we sought to characterise their spatio-temporal dynamics." (PMID 38267413, 2024). "The prolonged tumour dwell-time of CCR7+ DCs, which maintain high levels of PD-1 ligand expression but downregulate expression of genes enabling effector function, suggests that these cellular interactions are potentially deleterious." (PMID 38267413, 2024). "We report that CCR7+ DCs are the dominant DC population that migrate to the dLN, but a subset remains tumour-resident despite CCR7 expression." (PMID 38267413, 2024). "Dendritic cells (DCs) capture tumour antigens and upregulate the chemokine receptor CCR7, which directs their migration to secondary lymphoid organs where they present antigens to T cells." (PMID 38267413, 2024). "Pan-cancer analysis revealed that CCR7 was highly expressed in various tumours and that the high CCR7 expression group had better overall and disease-free survival in pan-cancer." (PMID 38762550, 2024). "It has been suggested that CCR7 plays binary roles in cancer; the overexpression of the CCR7/CCL21 axis is associated with lymph node metastasis of various cancer types, and at the same time, CCR7 tends to potentiate immune cell movement to tumours." (PMID 38256152, 2024). "To further demonstrate that tumour CCR7+ DCs arise from cDC precursors, we examined Kaede-green DCs 5 h post-photoconversion, which should harbour few CCR7+ DCs because newly-entered DCs would have little time to acquire the CCR7+ activation programme." (PMID 38267413, 2024). "Altogether, these data demonstrate that CCR7+ DCs are critically positioned to regulate anti-tumour cytolytic activity, including via TNF-superfamily ligands such as OX40L, and PVR." (PMID 38267413, 2024). "On the one hand, CCL21 interacts with CCR7 to control the transfer of immune cells such as DCs and T cells to lymphatic vessels and lymph nodes, which in turn enhances the anti-tumor immune response." (PMID 37307828, 2024). "Some tumor-derived metabolites, such as oxysterols and lactic acid, restrain the CCR7-mediated migration and antigen presentation capability of DCs." (PMID 38008741, 2023). "In another approach, CAR-T cells have been enhanced by dual overexpression of CCL19 and IL-7, with CCL19 here being another ligand of CCR7 which leads to increased migration of endogenous immune cells into the tumor." (PMID 36167831, 2023). "The double-transduced T cells mimicked the behavior of one of the singular receptors in each organ: they resembled the pattern of CCR4 in the tumor and CCR7 in the draining lymph node." (PMID 37301772, 2023). "The other batch contained CCR4 and CCR7, which conveyed T cell enrichment in the tumor-draining lymph nodes." (PMID 37301772, 2023).
tumor (continued). "In PAAD, sensory-neuron-derived mediators CXCL10 and CCL21 pass through complementary receptors CXCR3 and CCR7 on tumor cells, activating AKT, MEK, and RAC signaling pathways in tumor cells to mediate migration." (PMID 36900158, 2023). "CCR7 expression was found to be significantly increased in tumor samples compared with that in matched normal samples." (PMID 37208608, 2023). "An even more extreme example is that dysregulation of CCL19, a homeostatic chemokine that interacts with CCR7 to play a crucial role in the development of lymphoid organs, showed both tumor-suppressive and oncogenic effects in cancer." (PMID 37198402, 2023). "C-C Motif Chemokine Receptor 7 (CCR7) can be pathologically expressed by tumor cells, which drives tumor growth and metastasis and increases their homing behavior, particularly towards lymphatic organs." (PMID 37895310, 2023). "To further explore the relationship between the CCR7/CCL19 chemokine axis prognostic risk model and immunity, we explored the relationship between riskScores and immune infiltrating cells, tumor microenvironment, ssGSEA scores and HLA genes." (PMID 37864213, 2023). "CCR7-loaded nanoparticles would limit their effects directly to the tumor, decreasing bystander effects of the therapy compared an anti-CCR7 antibody which works systemically." (PMID 38022679, 2023). "While TNF-α is a weak stimulator of CCR7 expression, it counterbalances the emergence of M2-like tumor macrophages." (PMID 37415975, 2023). "Increased expression of CCR7 is directly related to the incidence of metastases to cervical lymph nodes and tumor progression." (PMID 37600570, 2023). "Data from several resources also reported the consistency of raising CCR7 levels in regulating different types of tumor metastasis." (PMID 37600570, 2023). "The tumor-derived oxysterols were observed to inhibit DCs surface CCR7 expression by binding with nuclear liver X receptor (LXR), therefore impairing DCs migration and anti-tumor responses." (PMID 37828561, 2023). "We confirmed that specific and differential pattern of CCR6, CCR7 mRNA expression levels was manifested in NSCLC tumor cells." (PMID 37316552, 2023). "A pervious paper has demonstrated that M1 macrophages, well-characterized activated macrophages with antitumorigenic properties, inhibit MC38 tumor growth and they express CCR7 and migrate toward a CCL21 gradient." (PMID 37664721, 2023). "Mechanistically, CCL21 induced Erk1/2 and Akt phosphorylation in tumor cells and CCR7 knockdown abrogated Akt and Erk1/2 activation." (PMID 37314567, 2023). "Hybridize immunogenic tumor derived exosome (TEX) with CCR7 retained dendritic cell membrane vesicle (DCMV), and adjuvanted by MPLA, to develop a novel nanovaccine (Hy‐M‐Exo), which can target in lymph nodes via the CCR7‐CCL21 way." (PMID 37092579, 2023). "Chemokine receptor 7 (CCR7)-induced neutrophil migration to draining lymph nodes improves the ability of neutrophils to deliver antigen and encourages the development of tumor immunity." (PMID 36761433, 2023). "The analysis of mregDCs should be integrated in further studies of tumor-infiltrating DC subsets by using markers such as CCR7, LAMP3 and CD11c to distinguish them from other DC subsets." (PMID 37190135, 2023). "CCR7 inhibition has been shown to be an important factor for tumor cell invasiveness in several different cancer types, and our data suggest that this is also true for GBM." (PMID 37314567, 2023). "When analyzed on day 5 after T-cell injection, CD83 was more upregulated in the intratumoral CCR7+ CAR-T cell population than in CCR7− CAR-T cells in the tumor and T cells in the spleen." (PMID 36906640, 2023). "On the one hand, we found that CCR7 was highly expressed in tumor samples in the TCGA database (p < 0.05), while the difference in CCL19 was not statistically significant (p = 0.328)." (PMID 37864213, 2023).